U8 (U8 small nucleolar RNA )
Synonyms: LOC124900358
Gene: Small nucleolar RNA gene on chromosome 15 (30,581,184 to 30,581,316, forward strand). Ensembl gene ENSG00000207430.
Gene Ontology:
Biological process: RNA processing
Cellular component: nucleolus
Homologues: Orthologues: chimpanzee U8 (98% identical), rabbit U8 (54% identical). Paralogues in human: U8 (100% identical), U8 (99% identical), U8 (98% identical), U8 (80% identical), U8 (78% identical), U8 (77% identical), U8 (76% identical), U8 (72% identical), U8 (71% identical), U8 (70% identical), U8 (69% identical), U8 (65% identical), and 1 more.